TRAF6 (TNF receptor associated factor 6)
Diseases named in the same sentence as TRAF6 in open-access papers (continued):
Sharing a sentence is not in itself a finding about the gene and the disease.
melanoma (continued). "Recently, EGCG has also been found to inhibit melanoma cell invasion and migration by attenuating the activity of tumor necrosis factor (TNF) receptor-associated factor 6 (TRAF6)." (PMID 29565284, 2018). "Knockdown of TRAF6 significantly blocked melanoma cell invasion and metastasis in vitro and in vivo." (PMID 26769849, 2016). "Our study showed that TRAF6 plays a critical role in melanoma and is a potential chemotherapy or prevention molecular target." (PMID 27791197, 2016). "Our previous results demonstrated that TRAF6 is over-expressed in clinical melanoma tissues and melanoma cell lines, such as SK-MEL-5 and -28." (PMID 27791197, 2016). "Consistent with the in vitro data, knocking down TRAF6 led to significant delay in growth of xenografted melanoma tumors and resulted in smaller tumors compared with xenografts expressing scrambled shRNA." (PMID 26769849, 2016). "We present evidence showing that TRAF6 is overexpressed in clinical melanoma tissues, including metastatic melanoma." (PMID 26769849, 2016). "In our previous study, we demonstrated that TRAF6 is overexpressed in melanoma and regulates melanoma metastasis through the ubiquitination of CD147 to regulate the expression of MMP-9." (PMID 27791197, 2016). "Our data implicate TRAF6 as a potential molecular target for chemotherapy and prevention against malignant melanoma." (PMID 26769849, 2016). "To study the effect of TRAF6 on melanoma cell growth, we generated stable knock down of TRAF6 by shRNA in SK-MEL-5 and SK-MEL-28 cell lines with independent shRNAs targeting sequences." (PMID 26769849, 2016). "Mutation of the TRAF6 ubiquitination sites in BSG blocks its ability to induce MMP-9 expression and reduces melanoma cell invasion." (PMID 27791197, 2016). "Although studies have shown that TRAF6 has oncogenic activity, the role of TRAF6 in melanoma is unclear." (PMID 26769849, 2016). "Our previous results demonstrated that TRAF6 is overexpressed in melanoma and that TRAF6 knockdown dramatically attenuates tumor cell growth and metastasis." (PMID 27791197, 2016). "A previous study showed that TRAF6 knockdown inhibits the proliferation, invasion and migration of melanoma cells, indicating that TRAF6 plays a critical role in melanoma." (PMID 27791197, 2016). "In particular, we demonstrated that BSG is a novel interacting partner of TRAF6, which regulates BSG membrane recruitment, BSG-dependent MMP9 expression and melanoma cells invasiveness via K63-linked ubiquitination." (PMID 26769849, 2016). "Here, we report that TRAF6 is overexpressed in primary as well as metastatic melanoma tumors and melanoma cell lines." (PMID 26769849, 2016). "In this study, we found that EGCG significantly attenuated the proliferation and metastasis of melanoma, a finding that is consistent with the results of our previous study concerning the effects of TRAF6 in melanoma." (PMID 27791197, 2016). "Moreover, we demonstrate that inhibition of TRAF6 with cinchonine leads to a significant reduction in the growth of melanoma cells both in vitro and in vivo." (PMID 37484971, 2023). "Therefore, it has been found that TRAF6 is overexpressed in various types of cancer including pancreatic, liver, lung, head and neck, breast, colorectal cancers, and melanoma along with inflammatory, autoimmune and neurodegenerative disorders." (PMID 38004473, 2023). "Additionally, inhibiting TRAF4, TRAF5, or TRAF6 improved retinoic acid sensitivity and reduced colony formation in ovarian cancer and melanoma cells." (PMID 37389738, 2023). "Importantly, targeting TRAF6 with cinchonine, a TRAF6 inhibitor, effectively suppressed the growth of melanoma cells by inducing autophagy and apoptosis through the TRAF6/c‐Jun/ATG16L2 signaling pathway." (PMID 37484971, 2023). "The reason why TRAF6 inhibition only affects MeWo cells in this study could be attributed to the upregulation and hyper-activation of TRAF6 in melanoma." (PMID 37389738, 2023).
melanoma (continued). "In this study, we found that TRAF4, TRAF5, and TRAF6 were upregulated in several TCGA cancer cohorts and cancer cell lines, especially in ovarian cancer and melanoma cell lines, indicating their potential correlation with retinoic acid sensitivity in these cells." (PMID 37389738, 2023). "Targeting TRAF4, TRAF5, or TRAF6 could be a promising strategy for inhibiting ovarian cancer and melanoma cell proliferation." (PMID 37389738, 2023). "Our results suggested that suppressing TRAF4, TRAF5, or TRAF6 can decrease the proliferation of ovarian cancer and melanoma cells and improve the sensitivity of these cells to retinoic acid treatment, probably by regulating cell apoptosis-related signaling pathways." (PMID 37389738, 2023). "Moreover, TRAF6 was observed to be overexpressed in primary and metastatic melanoma tumors, as well as in some melanoma cell lines." (PMID 37389738, 2023). "Furthermore, TRAF6 has been shown to support the malignant phenotype of melanoma cells by activating the NF-κB/FGF19 signaling pathway." (PMID 36010884, 2022). "In addition, TRAF6 modulates invasion as well as metastasis of melanoma via Basigin ubiquitination and BSG-dependent MMP9 induction." (PMID 36202787, 2022). "Therefore, TRAF6 can enhance melanoma invasion and metastasis through the regulation of MMP9 production." (PMID 33430277, 2021). "TRAF6 shows an E3 ubiquitin ligase activity and is expressed at a high level in melanoma." (PMID 33430277, 2021). "Therefore, TRAF6 has become a potential therapeutic target for multiple tumors, such as multiple myeloma, liver cancer, and melanoma." (PMID 32905356, 2020). "In addition, the neurotrophin signaling showed distinct rewiring, where CD271 expression correlated with switched activity of JNK and TRAF6 pathways in melanoma and melanocytes." (PMID 31118427, 2019). "Confirming the inability of TRAF6‐deficient Tregs to enforce tumor‐associated immune tolerance, Traf6fl/flFoxp3Cre+ mice failed to support the growth of implanted B16 melanoma cells." (PMID 30886050, 2019). "Therefore, this study suggests that EGCG is an E3 ubiquitin ligase inhibitor and inhibits melanoma cell growth and metastasis by targeting TRAF6." (PMID 30585192, 2018). "For instance, TRAF6 regulates melanoma invasion and metastasis through ubiquitination of CD147." (PMID 28117675, 2017). "In addition, ubiquitination of membrane-localized CD147 by TRAF6 activates signaling pathways enhancing melanoma invasion and metastasis." (PMID 28117675, 2017). "Indeed, TRAF6 regulates melanoma invasion and metastasis through ubiquitination of membrane-localized CD147." (PMID 28117675, 2017). "Taken together, these findings show that EGCG is a novel E3 ubiquitin ligase inhibitor that could be used to target TRAF6 for chemotherapy or the prevention of melanoma." (PMID 27791197, 2016). "The oncogenic function of TRAF6 in melanoma progression was demonstrated by the findings that knockdown of TRAF6 in melanoma cells resulted in diminished malignant phenotypes both in vitro and in vivo, suggesting that TRAF6 plays a critical role in melanoma metastasis." (PMID 26769849, 2016). "Our study uncovered previously unrecognized roles of TRAF6 in melanoma invasion and metastasis." (PMID 26769849, 2016). "Furthermore, we conducted xenograft study in nude mice to examine the effect of knocking down TRAF6 on melanoma cell growth in vivo." (PMID 26769849, 2016). "In summary, we uncovered that TRAF6 is overexpressed in human melanoma tissues." (PMID 26769849, 2016). "Taken together, our findings indicate that TRAF6 is involved in regulating melanoma invasion and metastasis, suggesting that TRAF6 may be a potential target for therapy or chemo-prevention in melanoma." (PMID 26769849, 2016). "In view of our data showing that TRAF6 contributes to melanoma metastasis in vitro and in vivo, we tested whether TRAF6 might regulate the expression of MMPs." (PMID 26769849, 2016).
melanoma (continued). "Given that TRAF6 is overexpressed in metastatic melanoma, we hypothesized that TRAF6 might mediate melanoma invasion and metastasis." (PMID 26769849, 2016). "Hence, we measured the expression of these apoptosis‐related proteins by western blotting, which showed that the levels of cleaved PARP, and cleaved Caspase‐9 were significantly increased and the level of BCL2 was greatly decreased in TRAF6‐knockdown melanoma cells." (PMID 37484971, 2023). "Considering these findings, targeting TRAF6 could be a promising therapeutic approach for melanoma." (PMID 37484971, 2023). "Thus, TRAF6 represents a potential therapeutic target for the treatment of melanoma." (PMID 27791197, 2016). "However, the role of TRAF6 in cancer invasion and metastasis, particularly in melanoma, is unclear." (PMID 26769849, 2016). "Since RSK is involved in the control of mRNA translation and is also a potent modulator of inflammation through the TRAF6-IKK-NF-κB pathway, we hypothesize that RSK inhibition in melanoma may globally reduce the bioenergetic charge and associated oxidative stress in melanoma cells." (PMID 39658088, 2025). "By flow cytometry, we analyzed the expression of proteins, including TLR3, TRAF6, and SNCA, as a marker of macrophages that have taken up Fibroblast-derived, keratinocyte-derived, and melanoma-derived melanosomes, respectively (workflow)." (PMID 38719996, 2024). "In this study, we present evidence supporting the role of TRAF6 in the downregulation of ATG16L2 through c‐Jun, which ultimately triggers both apoptosis and autophagy in melanoma cells." (PMID 37484971, 2023). "Taken together, our results indicate that the TRAF6/c‐Jun/ATG16L2 signaling axis plays an essential role in the crosstalk between apoptosis and autophagy in melanoma." (PMID 37484971, 2023). "Here, we found that TRAF6 participates in the survival pathway in melanoma cells through ATG16L2, and our previous studies demonstrated that TRAF6 promotes the malignant phenotype of melanoma cells." (PMID 37484971, 2023). "The same immunoblot shows that levels of TRAF6 are comparable in the pancreatic SU86 and melanoma A375 cell lines." (PMID 36781840, 2023). "This is also the case for CD147, and it has been reported that the ubiquitin ligase TRAF6 ubiquitylates CD147 to facilitate its recruitment to the plasma membrane without affecting its stability, leading to the promotion of melanoma invasion and metastasis." (PMID 35926707, 2022). "In melanoma, epigallocatechin-3-gallate decreased p-TAK1 expression and suppressed cancer cell growth and metastasis by targeting TRAF6 activity." (PMID 32764572, 2020). "After transfection with HA-AKT and HA-TRAF6, HA-IP was obtained from melanoma cells over-expressing or not FKBP51 and was assayed in vitro with the TRAF6-specific Ubc13/Uev1a ubiquitin-conjugating (E2) enzyme." (PMID 36781840, 2023). "Hence, we treated melanoma cells with cinchonine, a compound from the Cinchona alkaloid family that binds to the RING domain of TRAF6 and affects its function." (PMID 37484971, 2023). "High IRAK-M expression drastically decreased TRAF6 and calpastatin proteins in melanoma cells but did not change the levels in melanocytes." (PMID 32533049, 2020). "In the same fashion, CD271 signaling in melanoma does not rely on TRAF6, which is significantly downregulated." (PMID 31118427, 2019). "Furthermore, TRAF6 can directly interact with and ubiquitinate BSG leading to MMP9 induction, which serves as a mechanism for melanoma invasion and metastasis." (PMID 26769849, 2016). "Furthermore, TRAF6 directly interacts with BSG, which is important for the expression of MMPs during melanoma metastasis and induces the ubiquitination of BSG." (PMID 27791197, 2016).
melanoma (continued). "TRAF6 promotes the invasion and metastasis of melanoma, glioblastoma, gastric cancer and other tumors by overexpressing MMP-9, leading to malignant transformation of tumors and down-regulation of TRAF6 in A549 lung adenocarcinoma cells effectively reduces MMP9 expression." (PMID 32905356, 2020). "We also examined TRAF6 expression in different skin cancer cell lines and found that TRAF6 is highly expressed in melanoma cell lines (SK-MEL-5 and SK-MEL-28), compared with other cell lines, suggesting that TRAF6 might play an important role in melanoma." (PMID 26769849, 2016). "TRAF4 and TRAF6, noncanonical members of the TRAF family, are widely recognized as oncogenes in various human malignancies, including lung cancer, breast cancer, ovarian cancer, melanomas, neurogenic tumors, colon cancer, osteosarcoma, and pancreatic cancer." (PMID 37389738, 2023).
colorectal cancer (34 papers, 2017 to 2026). A primary or metastatic malignant neoplasm that affects the colon or rectum. "A significant association has been observed between TRAF6 expression and Duke's stage, differentiation capacity, and lymph node metastasis in colorectal cancer patients (P<0.05)." (PMID 38169510, 2024). "For instance, in colorectal cancer, UBE2V1 forms heterodimers with UBC13, where UBC13 provides catalytic activity while UBE2V1 enhances affinity with E3 ligases such as TRAF6, promoting K63-linked ubiquitin chain synthesis." (PMID 41446875, 2025). "For example, TRAF6 binds HIF-1α and mediates its K63-linked polyubiquitination, maintaining HIF1α’s stability and promoting colorectal cancer development." (PMID 38769340, 2024). "Knockdown of TRAF6 in colorectal cancer cells significantly up-regulated the protein levels of RIPK1 and p-RIPK1 and downstream p-RIPK3 and p-MLKL." (PMID 36604411, 2023). "In this study, we found that TRAF6 enhances the progression of colorectal cancer cells by inhibiting RIPK1-mediated necroptosis." (PMID 36604411, 2023). "KO-TRAF6 colorectal cancer cells showed better improvement in necroptosis, and we showed representative pictures of necroptosis at different stages, which demonstrated that TRAF6 protein expression can inhibit cell necrosis." (PMID 36604411, 2023). "KDM4B promotes the progression of colorectal cancer and glucose metabolism by promoting TRAF6-mediated AKT activation." (PMID 36765702, 2023). "TRAF6 enhances colorectal cancer progression and growth by nuclear shuttle regulation of the NF-κB/c-Jun signaling pathway." (PMID 36741260, 2023). "In conclusion, we demonstrated that TRAF6 promotes cancer cell progression by inhibiting necroptosis via RIPK1 in colorectal cancer cells." (PMID 36604411, 2023). "These experimental results suggest that TRAF6 inhibits necroptosis in colorectal cancer cells by inhibiting the RIPK1-RIPK3-MLKL signaling axis, resulting in cancer cell progression." (PMID 36604411, 2023). "The effect of TRAF6 in colorectal cancer is still controversial, and more research investment is needed to affect the way of tumor cell death." (PMID 36604411, 2023). "It was then shown that TRAF6 can be significantly linked to RIPK1 by polyubiquitination in HCT116 and SW480 colorectal cancer cells." (PMID 36604411, 2023). "To further investigate this phenomenon, we examined TRAF6 mRNA and protein levels in clinical tissue specimens from ten colorectal cancer patients and divided them into TRAF6 Low and TRAF6 High groups in order of median TRAF6 protein levels." (PMID 36604411, 2023). "We searched for colorectal cancer patient data from the GEO database and plotted TRAF6 expression-related survival curves, and the analysis showed that patients with high TRAF6 expression had a poorer survival prognosis." (PMID 36604411, 2023). "The recent study found that TRAF6 inhibits necroptosis in colorectal cancer cells via the RIPK1/RIPK3/MLKL signaling pathway." (PMID 36604411, 2023). "Transient and stable overexpression of TRAF6 in colorectal cancer cells significantly decreased the protein levels of RIPK1 and p-RIPK1 as well as downstream p-RIPK3 and p-MLKL produce inhibition." (PMID 36604411, 2023). "The present study reports the detailed mechanism by which TRAF6 regulates necroptosis in colorectal cancer cells." (PMID 36604411, 2023). "In conclusion, we demonstrate for the first time that TRAF6 reduces necroptosis in colorectal cancer cells by directly degrading RIPK1 protein levels and inhibiting the RIPK1-RIPK3-MLKL signaling axis, resulting in the promotion of tumor progression." (PMID 36604411, 2023). "We validated the initial TRAF6 expression levels in some colorectal cancer cell lines, including HCT116 cells and SW480 cell lines." (PMID 36604411, 2023).